BDNF (brain derived neurotrophic factor)
Diseases named in the same sentence as BDNF in open-access papers (continued):
Sharing a sentence is not in itself a finding about the gene and the disease.
diabetes (continued). "Additionally, stress and depression, common in diabetes, lower BDNF through cortisol, while sedentary lifestyles and poor diets exacerbate the decline." (PMID 39712817, 2024). "Also, the available literature tells of the significant role of BDNF in diabetes and other diseases." (PMID 39712817, 2024). "Furthermore, an exaggerated mTOR pathway in diabetes inhibits BDNF signaling leading to neuroinflammation and synaptic dysfunction in diabetic encephalopathy." (PMID 38006577, 2024). "Third, metabolic variables were not collected, which prevented us from identifying if biological variables like blood glucose levels, diabetes, blood pressure, and circulating BDNF were also changing with physical fitness and self-reported mental health after a remote supervised exercise program." (PMID 38716241, 2024). "BDNF levels and function appear to be disrupted by and related to insulin resistance in diabetes." (PMID 39139674, 2024). "Data from a double-blind, placebo-controlled trial of rutin 500 mg daily for 3 months showed significant improvements in metabolic measures, brain-derived neurotrophic factor (BDNF), and markers of inflammation and oxidative stress in patients with type 2 diabetes mellitus (T2DM)." (PMID 38398046, 2024). "Due to its role in neuronal health and metabolism, increasing BDNF levels could offer a therapeutic approach to managing diabetes-related complications." (PMID 39712817, 2024). "BDNF levels were affected by both diabetes pathology and cognitive processes in our patients." (PMID 36936159, 2023). "Also, the expression level of BDNF mRNA in the diabetes group was significantly decreased compared to the control group (P < 0.0001)." (PMID 37081849, 2023). "A study performed on 4-week-old prediabetic db/db mice has shown that treatment with BDNF may prevent an increase in blood glucose levels, demonstrating the preventive potential of BDNF against the development of diabetes." (PMID 38137892, 2023). "Other mechanisms that may be involved include the effect of diabetes on inflammation and reduced growth factors, especially brain-derived-neurotrophic-factor (BDNF)." (PMID 38148890, 2023). "We also showed that diabetes induced by STZ can reduce the amount of BDNF." (PMID 37970441, 2023). "However, diabetes-induced neural apoptosis was less in DMEX-G than DM-G with observed raises in the BDNF/TrkB signaling pathway as well as decreases in Fas/FasL-mediated and mitochondria-initiated pathways." (PMID 35743182, 2022). "BDNF methylation is very poorly explored in the context of diabetes." (PMID 35225959, 2022). "There is substantial evidence linking BDNF to the progression of type 2 diabetes mellitus (T2DM)." (PMID 35225959, 2022). "Multivariable logistic regression analysis indicated that serum apelin (OR = 0.304, 95%CI: 0.104–0.886, P = 0.029), as well as education levels, diabetes duration, cardiovascular disease, serum HbA1c, HDL-C, creatinine, and BDNF, were independent risk factors of MCI in patients with T2DM." (PMID 35610700, 2022). "Drop-out at the 1-year re-evaluation was significantly associated with older age and higher Killip class but not with diabetes, the sBDNF level, or presence of the BDNF Val66Met polymorphism." (PMID 35459929, 2022). "Moreover, in patients with diabetes mellitus (DM), the serum and aqueous humor BDNF levels decreased." (PMID 35269763, 2022). "Our findings imply that assessing diabetes and BDNF-related markers in ACS patients could be used to screen high-risk groups for suicide." (PMID 35459929, 2022). "Even we have observed that diabetes has decreased the BDNF mRNA expression in zebrafish." (PMID 36358486, 2022). "Meanwhile, the correlation between BDNF and insulin in different diabetes duration was analyzed." (PMID 35111074, 2021).
diabetes (continued). "This article is a summary of our work on investigating the relationship between VEGF- and BDNF-mediated MC viability in diabetes, the role and mechanism of BDNF in this process, and the therapeutic potential of BDNF-mediated MC survival and neuroprotection in DR and hypoxic BRB disorders." (PMID 34068807, 2021). "Therefore, IN BDNF appears to be a promising, non-invasive intervention that improves brain bioavailability for the treatment of cognitive complications of diabetes." (PMID 35058808, 2021). "Moreover, ART/Met treatment preserved parasympathetic innervation (AChE and BDNF) in SGs to alleviating diabetes-induced hyposalivation likely through rescuing central SSN damage." (PMID 34987398, 2021). "Moreover, ART/Met preserved parasympathetic innervation (AChE and BDNF expression) in SGs to alleviate diabetes-induced hyposalivation likely through rescuing central SSN damage." (PMID 34987398, 2021). "In experimental studies, treatment with BDNF could prevent the development of diabetes in prediabetic db/db mice." (PMID 34215825, 2021). "Nevertheless, diabetes and its various complications generally lead to a decrease in BDNF level." (PMID 34987398, 2021). "Their study showed that diabetes reduced the expression of BDNF in the sensory and motor roots." (PMID 32012942, 2020). "Decreased levels of BDNF and TrkB are observed in rats with diabetes-induced cognitive dysfunction." (PMID 32425784, 2020). "Moreover, the authors observed that in women with type 2 diabetes, the longer the duration of diabetes, the lower the BDNF concentration." (PMID 32012942, 2020). "This study suggested that endurance training may have the potential to compensate for the reduced expression of BDNF in diabetes neuropathy." (PMID 32012942, 2020). "The serum level of BDNF was higher in the control group than in the 10-week diabetes rat group." (PMID 32012942, 2020). "Moreover, the level of BDNF in the retinal homogenate of both the three-week and 10-week diabetes rat groups was lower than in the control group." (PMID 32012942, 2020). "Patients in the late stages of diabetes mellitus show a reduction of BDNF in plasma, suggesting that its administration could be beneficial for this kind of patient." (PMID 32443765, 2020). "In addition, the rat model of diabetes exhibits lower hippocampal BDNF mRNA levels compared to control rats, while administration of ghrelin significantly upregulates BDNF mRNA levels in a rat model of diabetes." (PMID 33071750, 2020). "BDNF and its receptor TrkB mediate aspects of neuronal development and differentiation and are involved in whole-body energy homeostasis and diabetes." (PMID 33178692, 2020). "Our data suggest that muscle-derived BDNF may be a key factor mediating increased glucose metabolism in response to exercise, with implications for the treatment of diabetes and related metabolic diseases." (PMID 32327658, 2020). "Many studies have shown the correlation of BDNF with miRNAs in diabetes-induced neurodegeneration." (PMID 33374507, 2020). "Therefore, further studies are needed aiming to analyze the interaction between BDNF and lncRNAs in diabetes-induced neurodegeneration." (PMID 33374507, 2020). "Increased BDNF expression was found in atherosclerotic coronary arteries in humans, and decreased plasma BDNF level was observed in patients with metabolic syndrome, acute coronary syndrome and in type 2 diabetes mellitus." (PMID 30767081, 2019). "Circulating insulin-like growth factor- (IGF-) 1, vascular endothelial growth factor (VEGF), and brain-derived neurotrophic factor (BDNF) levels are often lower in individuals with diabetes mellitus (DM) and are important for repairing vascular and neuronal dysfunction." (PMID 30729134, 2019). "Furthermore, plasma levels of BDNF are inversely correlated with fasting plasma glucose levels, suggesting a potential role for BDNF in glucose homeostasis and diabetes." (PMID 31118969, 2019).
diabetes (continued). "It is important to identify the exact molecular pathways through which impaired BDNF signalling may lead to the exacerbation of depressive symptoms in diabetes." (PMID 31053872, 2019). "The observation that STZ-induced type 2 DM is associated with low plasma levels of BDNF and LXA4 further lends support to the concept that a deficiency of these endogenous molecules could predispose to the development of diabetes mellitus." (PMID 31823816, 2019). "Additionally, the present study further suggested that low BDNF levels were associated with high vWF levels even after adjustment for age, LDL levels, gender, and the presence of diabetes mellitus." (PMID 29409455, 2018). "Gender did not moderate the effects of exercise training on changes in BDNF or diabetes risk factors." (PMID 30363954, 2018). "The main findings found in the present study showed that the expression of AGE, RAGE, TGF- β1 and TGF- β1 receptor was significantly higher whereas the expression of BDNF and TrkB was significantly lower in different colon layers in the Diabetes group than in Control group." (PMID 29930382, 2018). "They hypothesized that AGE-induced BDNF release is a biological defense system in the early phase of diabetes, and chronic elevation of AGEs may induce depletion or downregulation of BDNF in platelets during the progression of T2DM." (PMID 29062839, 2017). "There is argument regarding the levels of serum BDNF in patients with diabetes mellitus (DM)." (PMID 28178976, 2017). "Considering the toxic action of AGEs and the protective roles of BDNF, it can be hypothesized that AGE-induced BDNF release is a biological defense system in the early phase of diabetes." (PMID 28178976, 2017). "Although the causality and mechanisms remain unclear, it is possible that the dynamics of BDNF release are dysregulated in diabetes patients, thus altering serum levels." (PMID 28178976, 2017). "BDNF administration can ameliorate diabetes in experimental animals." (PMID 28824543, 2017). "In our study, we found that BDNF expression in the retina decreased in the diabetic group compared with the control group, whereas transplanted NSCs prevented the effect of experimental diabetes on BDNF expression." (PMID 28341839, 2017). "The involvement of BDNF in diabetes has been studied from those aspects." (PMID 28178976, 2017). "Besides neurodegenerative disorders, some studies also focused on intrathecal injection of BDNF in T2DM, yet the number is limited and only based on neuropathic pain caused by diabetes in an animal model." (PMID 29062839, 2017). "It was demonstrated that circulating BDNF is influenced by age and gender, the presence of diabetes, and the use of benzodiazepines in different neurological diseases, correlates with total cholesterol, and BDNF is stored and released from platelets during activation." (PMID 27478486, 2016). "Indeed, in retinas of mice with streptozotocin-induced diabetes, reductions of both BDNF and synaptophysin have been reported, but these reductions were attenuated by the antioxidant lutein." (PMID 27123463, 2016). "Few studies have investigated the role of autophagy in BDNF-mediated protection against diabetes." (PMID 26503303, 2015). "On the other hand, diabetes induced significant downregulation of the neurotrophin BDNF." (PMID 24897298, 2014). "The present study was designed to clarify the neuroprotective effect of HupA against DACD using a rat model of diabetes and whether the neuroprotection mechanism involves BDNF and oxidative stress." (PMID 24857910, 2014). "In agreement, BDNF-immunoreactivity decreased in the retina from SE-housed diabetic animals as compared with non-diabetic animals, whereas EE housing prevented the effect of experimental diabetes on BDNF immunoreactivity." (PMID 25004165, 2014). "The results of these studies show that BDNF may have a role in the treatment of diabetes and dyslipidemia." (PMID 25587547, 2014).
diabetes (continued). "BDNF has also been shown to correlate with metabolic syndrome as well as diabetes." (PMID 24260264, 2013). "We also examined the effect of intravitreal administration of HMGB1 on the retinas of normal rats and whether constant GA intake suppresses diabetes-induced changes in BDNF expression." (PMID 23766563, 2013). "Furthermore, intraocular administration of BDNF rescued retinal dopaminergic amacrine cells from neurodegeneration in rats with diabetes." (PMID 23766563, 2013). "Glycyrrhizin significantly attenuated diabetes-induced downregulation of BDNF." (PMID 23766563, 2013). "The HMGB1 inhibitor GA attenuated diabetes-induced downregulation of BDNF in the retinas of rats." (PMID 23766563, 2013). "The mechanism by which the PARP inhibitor prevents diabetes-induced changes in the expression of BDNF, synaptophysin, GS, and caspase-3 in the retinas remains unclear." (PMID 24347828, 2013). "Brain-derived neurotrophic factor protein was detectable only in muscle satellite cells and was increased in diabetes patients compared with controls, consistent with the observation that global miRNA changes were opposite from those found during myogenic differentiation." (PMID 20353613, 2010). "Alterations in peripheral BDNF signaling could potentially be a common denominator for the metabolic syndrome spectrum, which ranges from impaired glucose tolerance to overt diabetes, to mild atherogenesis to clinical coronary artery disease." (PMID 20404913, 2010). "Thus, zinc insufficiency in people with diabetes might not only exacerbate inflammation and insulin dysfunction but could also diminish BDNF-mediated neural protection." (PMID 41142318, 2025). "In type 2 diabetes mellitus, the insufficient amount of BDNF can lead to neuro-retinal apoptosis and degeneration; thus, this review suggests that the exogenous administration of BDNF in DR could be taken into consideration." (PMID 40003672, 2025). "The activation of the BDNF/TrkB/CREB pathway reduces hepatic gluconeogenesis, glucose levels, leptin and food intake, inducing hepatic insulin signal transduction, elevating the number of glycolytic fibers in skeletal muscle and protecting against pancreatic β-cell loss in diabetes mellitus." (PMID 39857710, 2025). "Therefore, increasing BDNF levels is of critical importance for the prevention of diabetes." (PMID 40933306, 2025). "Therefore, our findings suggest that in the context of AIS complicated with diabetes, the disease-specific factors may override the potential BDNF-modulating effects of metformin." (PMID 41280373, 2025). "In addition to hyperglycemia-induced peripheral inflammation, similar molecular events occur in neuronal cells causing neuroinflammation which contributes to neurocognitive dysfunction and diabetes-induced dementia through downregulation of brain-derived neurotrophic factor (BDNF)." (PMID 39337483, 2024). "Additionally, diabetes may further affect patients’ cognitive function and emotional regulation by influencing the levels of neurotrophic factors, such as brain-derived neurotrophic factor (BDNF)." (PMID 39421064, 2024). "Addressing these factors may help restore BDNF levels and improve diabetes outcomes." (PMID 39712817, 2024). "Diabetes mellitus reduces brain-derived neurotrophic factor (BDNF) levels by enhancing oxidative stress or through other independent mechanisms, indicating that restoring the redox balance in DM may elevate BDNF levels and prevent associated complications and neurodegenerative diseases." (PMID 39347352, 2024). "The mechanism of action of BDNF in increasing CVD risk could be explained by the association between lower BDNF levels and known CVD risk factors such as lipid levels, older age, male gender, smoking, and diabetes mellitus." (PMID 38137853, 2023).
diabetes (continued). "However, a rodent study demonstrated that maternal diabetes leads to decreased BDNF expression, increased TNF-a concentrations, impaired cellular proliferation, and enhanced apoptosis in the offspring’s hippocampus, ultimately resulting in neurodevelopmental deficits." (PMID 37469977, 2023). "While research has shown that BDNF crosses the blood-brain barrier and that there is a correlation between brain and peripheral levels it may not be enough to fully understand the role of BDNF in neuropathology caused by diabetes." (PMID 36936159, 2023). "Given the broad distribution of BDNF throughout the body and its extensive range of functions, it is a frequently evaluated molecular target in metabolic and neurodegenerative diseases, including AD and diabetes, and for drug-targeting mechanisms as well, such as with RSG." (PMID 37508471, 2023). "In addition to diabetes, platelet levels have been determined as a predictive factor for BDNF." (PMID 36936159, 2023). "Considering the preventive aspects, careful attention is needed for ACS patients who have both diabetes and altered BDNF-related markers; however, further studies are needed to evaluate whether additional suicide prevention practices may be beneficial in this subpopulation." (PMID 35459929, 2022). "Besides the promotion of BDNF levels, we also found a BHB-induced BDNF activity in diabetic retina." (PMID 36077579, 2022). "Similarly, an imbalance of the circulating concentration of BDNF also mediates the pathophysiological process of many diseases, such as prostate cancer, benign prostatic hyperplasia, male infertility, diabetes erectile dysfunction, penile sclerosis, and bladder fibrosis." (PMID 36661494, 2022). "Because diabetes and the BDNF pathway are closely related to ACS and suicide, respectively, and the level and function of BDNF are disrupted in diabetes, suicidal behavior in ACS patients may be affected by a potentially complex relationship between diabetes and the BDNF pathway." (PMID 35459929, 2022). "In addition, although the interaction effects were not significant, diabetes was associated with a higher frequency of chronic SI only in patients with a low sBDNF level or with the BDNF Met/Met genotype." (PMID 35459929, 2022). "Indeed, its dysregulation has been reported in preclinical and clinical studies, evidencing decreased BDNF levels in a rat model of early retinal neuropathy induced by diabetes as well as in serum and aqueous humor of diabetic patients before DR clinical signs." (PMID 36077579, 2022). "Since BHB seems to impact on autophagy dynamics in cortical neurons and BDNF can act as a suppressor of neuronal and retinal autophagy, this study also aimed to investigate if the upregulation of retinal BDNF induced by BHB could impact on the retinal autophagy induced by diabetes." (PMID 36077579, 2022). "Replenishing BDNF or enhancing its downstream signaling pathway may be beneficial for diabetes." (PMID 33477900, 2021). "In addition, several comorbidities, such as abdominal obesity and diabetes mellitus, coexisting with HF can also alter the profile of myokines including irisin, myostatin, brain-derived neurotrophic factor (BDNF), and growth differential factor-11 (GDF-11) and lead to muscle weakness." (PMID 33520013, 2021). "Interestingly, other studies found that BDNF was negatively associated both T2D duration and FBS levels, suggesting that the decreased BDNF levels in T2D might be related to longer diabetes duration and higher glucose concentrations." (PMID 34215825, 2021). "Our data also indicate that the upregulation of BDNF and p-CREB by ARBs may contribute to their neuroprotective effects in diabetic individuals and could be selectively targeted to alleviate some of the depressive symptoms associated with diabetes." (PMID 31053872, 2019). "Hence, methods developed to deliver a combination of PUFAs (especially AA), LXA4 and BDNF may prevent development of diabetes mellitus (both type 1 and type 2)." (PMID 31823816, 2019).